EGFR (epidermal growth factor receptor)
Diseases named in the same sentence as EGFR in open-access papers (continued):
Sharing a sentence is not in itself a finding about the gene and the disease.
prostate tumor (continued). "DU145 is a prostate tumor cell line resistant to androgen deprivation therapy (ADT), while both PC9ER and H1975 express the EGFR-T790M mutation that predicts resistance to first-generation anti-HER1-TKI." (PMID 39479017, 2024). "In prostate tumor cells, the EGFR is phosphorylated and more active within membrane rafts." (PMID 35819726, 2022). "In view of our results, we propose that miR-3622b may be an important anti-cancer target for EGFR overexpressing prostate tumors." (PMID 27611943, 2016). "As a cell transforms to a malignant state, MEIS1/2 are epigenetically silenced in more aggressive prostate tumors and expression of tumor-suppressive proteoglycans is suppressed, leading to decreased regulation of oncogenic signaling through pathways such as TGFβ, EGFR, cMYC, WNT, and IGF1R." (PMID 32553107, 2020). "We conclude that the mPGES-1 gene may be considered a signature gene for identifying a subtype of rapidly progressing prostate tumours, which, in the case of overexpression of EGFR, may benefit from combined treatment with inhibitors of EGFR, tyrosine kinase and PGE2." (PMID 26113609, 2015). "In several Oncomine datasets, EGFR and/or ERBB2 mRNA levels also increased in prostate tumors compared to normal tissues." (PMID 31792211, 2019). "These interventions also blocked EGFR-mediated fibroblast and DU145 and PC3 human prostate tumour cell migration and transmigration of an ECM barrier, decreasing it to a background level." (PMID 16804520, 2006). "Therefore, β-catenin levels were assessed by Western blotting in prostate tumour cells after different treatments with the GHRH-R antagonist and the EGFR inhibitor, individually or in combination." (PMID 39456984, 2024). "Moreover, recombinant humanized ERBB2 monoclonal antibody pertuzumab prevents dimerization of ERBB2 with EGFR and ERBB3 to prevent activation of downstream pathways, which is demonstrated to be inhibiting breast and prostate tumor growth." (PMID 38216592, 2024). "There was a trend that EGFR expression was increased in metastatic lesions compared with primary prostate tumors, however, the statistical significance was not achieved." (PMID 30134822, 2018). "Although the EGFR target is present in the most frequent cancers, such as breast and prostate tumours, the benefits of anti-EGFR therapy plus cytotoxic agents are not yet apparent in these cases." (PMID 18506149, 2008). "Therefore, the observed cross-talk between the AR and EGFR axes leads to the assumption that EGFR-induced EMT and androgen-independence could occur simultaneously in prostatic tumor cells." (PMID 23185449, 2012).
acne (46 papers, 2006 to 2026). An inflammatory process of the sebaceous glands which is characterized by comedones, nodules, papules and/or pustules on the skin. "The current study effectively refutes this misconception and provides clear evidence that severe acne caused by anti-EGFR inhibitors is, in fact, a sign of adverse reactions to the medication." (PMID 36980549, 2023). "Skin adverse events caused by EGFR-TKIs include rash/acne-like rash, dry skin, itching, scalp damage (alopecia folliculitis, hirsutism), and inflammation of nails/periungual tissues." (PMID 37089959, 2023). "The most common dermatologic reactions caused by anti-EGFR antibodies are acne-like rash, cracking, dryness, infection of the fingernails or toenails, itching, and redness, whereas purpura is rare." (PMID 30646927, 2019). "It is used for the treatment of acne vulgaris and is recommended for patients with acne due to skin damage caused by EGFR‐TKIs, since there have been reports that oral retinoic acid has been successful in treating skin disorders caused by EGFR‐TKI therapy." (PMID 38379420, 2024). "EGFR‐TKIs cause sterile acne, but bacterial infections, such as Staphylococcus aureus, may develop after prolonged periods of EGFR‐TKI treatment." (PMID 38379420, 2024). "However, caution is necessary, as a prior predisposition to folliculitis and acne may be associated with cutaneous adverse events during the use of EGFR inhibitors." (PMID 36990917, 2023). "Therefore, terms that imply a similarity with acne, such as “acneiform rash”, “acneiform follicular rash”, “acne-like rash”, “maculopapular rash”, or “monomorphic pustular lesions”, should not be used to describe the papulopustular rash associated with anti-EGFR therapy." (PMID 20680104, 2010). "Additionally, a larger sample size would increase the statistical power and validity of the results, as well as the ability to understand specific consequences of treatments such as anti-epidermal growth factor receptor therapy, which commonly cause an acne-like rash." (PMID 17565347, 2007). "Among other antitumor drugs in the HNC field, namely the epidermal growth factor receptor (EGFR) antibody cetuximab, an association between the adverse drug effect in the sense of acne-like skin changes and the therapy response is known." (PMID 38420014, 2024). "Among the 21 common targets of P. pterocarpum and acne, five targets - EGFR, MMP1, MMP2, MMP9, and MMP13 - were selected as the core targets because of their direct involvement in the relaxin signalling pathway." (PMID 39347283, 2024). "In patients previously treated with radiation therapy, EGFR inhibitor-induced acne-like rash was found to spare the previously irradiated body regions due to radiation-induced follicular loss." (PMID 36708507, 2023). "The research examined the effects of gender, age, and acne severity in patients treated with anti-EGFR inhibitors and found that male patients and younger age groups were more likely to experience a higher incidence of severe acne due to the treatment." (PMID 36980549, 2023). "Honeysuckle was effective in reducing the incidence and severity of EGFR-TKIs-induced acne-like rash by 10%–21% and faster recovery of pruritus compared with conventional treatment (minocycline)." (PMID 37089959, 2023). "Common adverse effects seen with the use of EGFR inhibitors were diarrhoea, rashes and acne, and the rate of serious adverse effects were comparable among the three studies." (PMID 34833470, 2021). "Acne and hypomagnesemia are frequently experienced by patients receiving anti-EGFR mAbs, and incidence rates of these AEs for patients receiving HLX07 were 21.1% and 15.8%, respectively." (PMID 33713216, 2021). "Relevant to cancer control, acne is inducible not only by Apert-like mutagenic FGFR2 activation but also by epidermal growth factor receptor (EGFR) inactivation, either by homozygous knockout or targeted drug inhibition." (PMID 34007277, 2021).
acne (continued). "Consistent with this, prevention of EGFR inhibitor-induced acne by skin irradiation is attributable to FGFR2 downregulation; FGF7-activated FGFR2b causes TGFα-induced EGFR signaling, completing a homeostatic FGFR2-EGFR control loop." (PMID 34007277, 2021). "Acne‐like skin reactions frequently occur in patients undergoing treatment with drugs inhibiting the epidermal growth factor receptor." (PMID 31199595, 2019). "The most frequently reported AEs with currently approved EGFR-TKIs (gefitinib, erlotinib, afatinib, and osimertinib) include diarrhea, rash/acne, and dry skin." (PMID 30790152, 2019). "Additional treatments for EGFR-TKI-associated rash include medium- to high-potency topical corticosteroids and isotretinoin at doses lower than those used for acne." (PMID 30588353, 2018). "Dermatologic AEs, such as rash and acne, are also commonly observed with EGFR TKIs, and patient education should be provided at the initiation of therapy." (PMID 30588353, 2018). "This research implies that MMPs and EGFR contribute to the development of acne and that lowering them may improve the effectiveness of therapy." (PMID 39347283, 2024). "EGFR-TKIs-induced rash/acne-like rash mostly occurs 1 week-2 weeks after targeted drug therapy." (PMID 37089959, 2023). "Some common adverse effects due to the use of EGFR inhibitors were diarrhea, rashes and acne." (PMID 34833470, 2021). "The rash associated with EGFR TKI use presents as the sudden onset of a papulopustular eruption; it is distinct from acne vulgaris in that it is associated with the characteristic papules and pustules, but there is a distinct absence of comedones (Eaby-Sandy, Grande, & Viale, 2012)." (PMID 29670808, 2016). "Since these EGFR antagonists can induce severe acne-like rash toxicity, hypomagnesia and diarrhea, toxicity might have prevented protracted therapy." (PMID 23782513, 2013). "Acne rash may therefore play a role as a surrogate marker of the efficacy of EGFR inhibition." (PMID 19293797, 2009). "By modulating key structural genes like ELN, FN1, EGFR, and TIMP3, F3TAC supports ECM remodeling and wound healing, essential for addressing inflammation and tissue repair in acne-prone skin." (PMID 39684852, 2024). "The core targets - EGFR, MMP1, MMP2, MMP9, and MMP13 - that directly participate in the relaxin signalling pathway are useful in managing acne by targeting these core targets." (PMID 39347283, 2024). "In the FLAURA phase 3 trial, 58% of patients treated with osimertinib developed a rash or acne, as opposed to 78% with standard EGFR TKI." (PMID 40422529, 2025). "Although adapalene plays crucial roles in antiproliferative and anti‐inflammatory pathways, the therapeutic mechanism of action of adapalene in EGFR‐TKI‐induced acne‐like eczema is not clear." (PMID 38379420, 2024). "Specifically, the modulation of EGFR and various MMPs (MMP1, MMP2, MMP9, and MMP13) through the relaxin signalling pathway appears to be a pivotal mechanism by which P. pterocarpum exerts its anti-acne effects." (PMID 39347283, 2024). "Although Afa is a potential EGFR-TKI for possible treatment of GC resistant to anti-EGFR mAb, Afa and EGFR form an irreversible covalent bond that produces painful side effects, such as rash/acne and diarrhea." (PMID 36145507, 2022). "Another study reported that the failure of EGFR homeostasis resulted in abnormal differentiation of sebocytes and the formation of acne-like eruptions, but there is still no clear explanation for the mechanism." (PMID 32252690, 2020). "Topical retinoids are not recommended as well, as the mechanisms of anti-EGFR and acne vulgaris eruption are different and they may also aggravate the skin irritation." (PMID 36990917, 2023).
acne (continued). "While the most common TRAEs were EGFR TKI class-related toxicities (diarrhea, rash/acne and stomatitis) and were not unexpected, the overall rate of grade ≥ 3 TRAEs was 58% compared with 31–49% in the LUX Lung 3, 6 and 7 studies (diarrhea: 5–14%; rash/acne: 9–16%; stomatitis: 4–9%)." (PMID 34253172, 2021). "Pharmacologic EGFR inhibition in nonresistant CRCs is associated with compensatory FGFR2-induced p38/MAPK upregulation that induces the downstream proinflammatory mesenchymal mitogen IL-1α which in turn promotes both sporadic acne and iatrogenic folliculitis." (PMID 34007277, 2021). "However, this method of oral administration of minocycline is a provisional procedure similar to the treatment of acne rash in adolescents, and there is no clear evidence that oral administration of minocycline has any effect on EGFR-TKI-induced eruptions." (PMID 32252690, 2020). "Patients should be reminded that although the rash associated with EGFR TKI therapy may have a similar appearance to acne, it should not be similarly treated, as anti-acne medications tend to be drying and may cause or exacerbate pruritus and irritation." (PMID 29670808, 2016). "Similarly, studies investigating isotretinoin for the treatment of eruptions induced by EGFR inhibitors did not include control groups, but consistent reports of isotretinoin use at doses lower than the ones used for acne support the recommendation for its use when other measures have failed." (PMID 36990917, 2023).
bladder tumors (46 papers, 1996 to 2025). "EGFR targeted NIR-PIT caused cell death in human bladder tumor cell lines in vitro and inhibited tumor growth in bladder tumor xenograft models." (PMID 36405499, 2021). "In addition, a significant increase in EGFR gene expression levels has been detected in invasive bladder tumors, compared with tumors of low malignancy, and EGFR has been associated with poor histological differentiation." (PMID 25295115, 2014). "We investigated the effect of two dual PI3K/mTOR (both mTORC1 and mTORC2) inhibitors, NVP-BEZ235 and NVP-BGT226, on SQ20B laryngeal and FaDu hypopharyngeal cancer cells characterised by EGFR overexpression, on T24 bladder tumor cell lines with H-Ras mutation and on endothelial cells." (PMID 22452803, 2012). "The presence of hEGR1 in tumours is shown here to be related to EGFR status and may be an important causal link to the growth and progression of bladder tumours." (PMID 17311025, 2007). "The activation of the MAPK and PI3K/mTOR signaling pathways were reported in about 70% of bladder tumors, including amplification of EGFR (9%)." (PMID 39219681, 2024). "The selectivity of this targeting arises from two factors: overexpressed EGFR on the surface of the tumor cells and greater tumor access due to extensive mucosal barrier disruption at the bladder tumor site compared to normal urothelium." (PMID 36082359, 2022). "To assess the selectivity of the NIR probe for binding to tissue bearing EGFR+ cells, we compared their binding properties with human bladder tumor and adjacent tissues." (PMID 36082359, 2022). "The EGFR signalling pathway is a central driver of tumourigenesis and a major drug target in various solid malignancies, including lung, breast, colon and bladder tumours." (PMID 34936728, 2021). "It has been shown that there was EGFR up regulation in muscle invasive in comparison with lower invasive bladder tumors which were also correlated with advanced tumor stage." (PMID 32795296, 2020). "Bladder tumor cells had significantly higher levels of EGFR and HER2 expressions compared with controls." (PMID 32795296, 2020). "EGFR expression has been reported as increased in various tumors of the bladder, colon, ovarian, and kidney." (PMID 29379789, 2017). "Our study found that recurring bladder tumors were more likely to express higher levels of EGFR in patients that received intravesical chemotherapy than in those who did not." (PMID 27870887, 2016). "As such, both intraluminal tumor cells and co-existing microscopic lesions overexpressing EGFR are more likely to survive instillation therapy and establish new bladder tumors." (PMID 27870887, 2016). "In an earlier study, we have shown upregulation of EGFR signalling in hypericin mediated PDT of bladder tumors." (PMID 25918252, 2015). "Activation of epidermal growth factor receptor (EGFR) also leads to stimulation of bladder tumor growth." (PMID 22922989, 2012). "Several large studies of EGFR expression using immunohistochemistry are concordant and report detectable levels in 72, 85, 96 and 84% of bladder tumour tissues and moderate or strong EGFR expression has been described in 27, 52, 42 and 47% of tumours." (PMID 21364580, 2011). "In this study, we evaluate the use of EGFR inhibitor Erbitux in combination with PDT to improve the tumor responsiveness in a bladder tumor xenograft model." (PMID 19878607, 2009). "Egr-1 is induced by epidermal growth factor (EGF) and has been shown to correlate to EGF receptor (EGFr) levels in bladder tumors." (PMID 19878561, 2009). "The role of EGFR in urothelial tumors was supported by the observation that 40%–60% of human bladder tumors overexpress EGFR mRNA and protein." (PMID 19171060, 2009). "Our results demonstrate the inhibition of hEGR1 induction in bladder tumour cell lines with the EGFR tyrosine kinase inhibitor gefitinib." (PMID 17311025, 2007).
bladder tumors (continued). "In bladder tumour samples, there was a significant correlation between hEGR1 mRNA detected by RT-PCR and EGFR detected by ligand binding, (P=0.042)." (PMID 17311025, 2007). "The sustained induction of hEGR1 by EGF in the RT112 bladder tumour cells for 24 and 48 h, in addition to the rapid induction seen at 1 to 2 h, indicates that further investigation of the role of hEGR1 and EGFR in bladder tumours is warranted." (PMID 17311025, 2007). "The involvement of hEGR1 in the EGFR stimulation of bladder tumour cells adds further detail to the downstream effects of intracellular signalling from EGFR in bladder tumours." (PMID 17311025, 2007). "The effect of EGF stimulation and its inhibition with gefitinib (‘Iressa’, ZD1839), an epidermal growth factor receptor (EGFR) tyrosine kinase inhibitor, has been investigated in two EGFR-positive human bladder tumour cell lines, RT112 and RT4." (PMID 15083203, 2004). "In another study, four different bladder tumour cell lines have been reported to show a dose-dependent inhibition of cell proliferation when treated with gefitinib, which correlated with the EGFR protein level." (PMID 15083203, 2004). "It has been shown that some high-grade bladder tumor patients had increased urinary level of EGFR." (PMID 32795296, 2020). "Similarly, BASQ-type bladder tumors show EGFR pathway deregulation, mainly through EGFR amplification, and are highly sensitive to EGFR inhibitors both in vitro and in xenograft models." (PMID 31562298, 2019). "Recent studies show that EGFR is positive in more than 60% of bladder tumors." (PMID 31480265, 2019). "We assessed EGFr functions in two urothelial cell lines where the UROtsa cell line is derived from normal epithelium and the T24 cell line is derived from a malignant bladder tumor." (PMID 29508172, 2018). "Moreover, a significant synergistic biological interaction was observed between EGFR negativity and intravesical chemotherapy in preventing bladder tumor recurrence (S = 2.991, AP = 0.591)." (PMID 27870887, 2016). "In all, this evidence suggests a “class-switch” from ErbB3 to EGFR/ErbB2 mediated ErbB signaling, mediated in part by collagen and fibronectin-stimulated integrin signaling, is a key mechanism promoting muscle-invasion of bladder tumors." (PMID 23383328, 2013). "Mithramycin causes greater sensitivity in NSCLC cells without EGFR mutation and possibly other cancer tissue types as seen by our results in bladder tumor cell line, HTB9." (PMID 24367505, 2013). "The EGFr is a recognized bladder tumor marker and high levels of EGFr are associated with non-papillary, high-grade invasive tumors." (PMID 19878561, 2009). "The results from triplicate experiments for 14 bladder tumour samples of known and previously reported EGFR status approached significance at the 95% confidence level (P=0.054, Mann–Whitney test), with a trend towards higher hEGR/actin ratios in EGFR positive tumours." (PMID 17311025, 2007). "The relationship between hEGR1 and EGFR in human bladder tumours was also investigated." (PMID 17311025, 2007). "Additionally, compared with primary UTUC, recurrent bladder tumors expressed higher levels of EGFR." (PMID 27870887, 2016). "Therefore, ETK may likely act as a downstream effector of EGF/EGFR to promote bladder tumor growth and metastasis." (PMID 21408190, 2011). "A combination of EGFR- and HER2-targeted PIT was proposed to target a broader range of bladder tumors with IR700-conjugated panitumumab (pan) and trastuzumab (tra), respectively." (PMID 36195918, 2022).